DGKB (diacylglycerol kinase beta)
Description:
Diacylglycerol kinase that converts diacylglycerol/DAG into phosphatidic acid/phosphatidate/PA and regulates the respective levels of these two bioactive lipids. Thereby, acts as a central switch between the signaling pathways activated by these second messengers with different cellular targets and opposite effects in numerous biological processes (Probable). Has a higher activity with long-chain diacylglycerols like 1,2-di-(9Z-octadecenoyl)-sn-glycerol compared to 1,2-didecanoyl-sn-glycerol (By similarity). Specifically expressed in brain, it regulates neuron-specific morphological changes including neurite branching and neurite spine formation (By similarity). [Isoform 2]: Does not associate with membranes but has a diacylglycerol kinase activity.
Synonyms: DGK-beta; DAGK2; KIAA0718; DGK
Tractability: Antibody: UniProt places it where antibodies can reach, with high confidence; its Gene Ontology location is reachable by antibodies, with high confidence; the Human Protein Atlas places it where antibodies can reach. PROTAC: ubiquitination databases record sites on it.
Target class: Enzyme; Transferase
Safety:
Unwanted effects reported when the protein is acted on. In parentheses: how it was acted on, where the effect was seen, and who reports it.
less weight gain (source: ClinPGx)
more weight gain (source: ClinPGx)
Gene: Protein-coding gene on chromosome 7 (14,145,049 to 14,974,833, reverse strand). Ensembl gene ENSG00000136267.
Subcellular location: Postsynaptic cell membrane; Cell membrane; Cytoplasm; Cytoplasm (Isoform 2)
Subcellular location (Human Protein Atlas): Plasma membrane; Nuclear speckles; Nucleoplasm
Pathways (Reactome):
Hemostasis: Effects of PIP2 hydrolysis
Gene Ontology:
Molecular function: ATP-dependent diacylglycerol kinase activity; lipid binding; calcium ion binding; kinase activity
Biological process: glycerolipid metabolic process; lipid phosphorylation; diacylglycerol metabolic process; intracellular signal transduction; phosphatidic acid biosynthetic process; platelet activation; phospholipase C-activating G protein-coupled receptor signaling pathway; signal transduction
Cellular component: cytoplasm; plasma membrane; postsynaptic membrane
Genetic constraint (gnomAD): Loss-of-function variants: 26 observed, 47.78 expected, observed/expected ratio (o/e) 0.54, 90% interval 0.4 to 0.75. The synonymous counts are far from expectation, so gnomAD's model fits this gene poorly and the ratio says little. Missense variants: 449 observed, 508.24 expected, observed/expected ratio (o/e) 0.88, 90% interval 0.82 to 0.95. Synonymous variants: 223 observed, 179.51 expected, observed/expected ratio (o/e) 1.24, 90% interval 1.11 to 1.39.
Homologues: Orthologues: chimpanzee DGKB (99% identical), macaque DGKB (99% identical), dog DGKB (99% identical), rabbit DGKB (97% identical), rat Dgkb (97% identical), mouse Dgkb (96% identical), pig DGKB (96% identical), tropical clawed frog dgkb (86% identical), zebrafish dgkb (69% identical), Drosophila melanogaster CG34384 (27% identical), Drosophila melanogaster rdgA (26% identical), Caenorhabditis elegans dgk-5 (24% identical), and 3 more. Paralogues in human: DGKG (62% identical), DGKA (55% identical), DGKD (29% identical), DGKH (29% identical), DGKQ (26% identical), DGKK (26% identical), DGKI (25% identical), DGKZ (24% identical), DGKE (23% identical).